BAP1 (BRCA1 associated deubiquitinase 1)
Diseases named in the same sentence as BAP1 in open-access papers (continued):
Sharing a sentence is not in itself a finding about the gene and the disease.
tumor predisposition syndrome (continued). "BAP1 tumor predisposition syndrome is characterized by BAP1-inactivated melanocytic tumors." (PMID 40649916, 2025). "The first describes the case of a woman with BUM (choroidal melanoma in her right eye and iris melanoma in her left eye) and basal cell carcinoma, who carried a pathogenic mutation in the BAP1 gene, justifying a genetic diagnosis of BAP1-associated tumor predisposition syndrome." (PMID 38892746, 2024). "Additionally, kidney involvement is frequently observed in conditions such as Birt–Hogg–Dubé syndrome, tuberous sclerosis, and BAP1 tumor predisposition syndrome, among others." (PMID 39201746, 2024). "In addition, kidney involvement is often observed in Birt–Hogg–Dubé syndrome, tuberous sclerosis, BAP1 tumor predisposition syndrome, etc.." (PMID 38390862, 2024). "It is well established that heritable risk to UM can be part of a tumor predisposition syndrome with variable manifestation and incomplete penetrance (BAP1-tumor predisposition syndrome, BAP1-TPDS), and the number of families with known oncogenic variants of the BAP1 gene has risen fast." (PMID 35920959, 2023). "Therefore, targeting the BAP1-CAMK2D (CAMKII delta) signaling axis is a promising therapeutic approach for most MMe cases and BAP1 tumor predisposition syndrome." (PMID 37479714, 2023). "The associated genetic condition is termed BAP1 tumor predisposition syndrome." (PMID 36641486, 2023). "In this context, we read with great interest the article of Vimercati and colleagues, who described a case of pleural mesothelioma (PM) in an 83-year-old man, with a story of environmental and working story of asbestos exposure, suspect for BAP1 tumor predisposition syndrome (BAP1-TPDS)." (PMID 37909022, 2023). "Germline BAP1 mutations underpin the BAP1 tumor predisposition syndrome (BAP1-TPDS)." (PMID 36980631, 2023). "BAP1 (Breast cancer susceptibility gene 1 associated protein 1 Tumor Predisposition Syndrome)." (PMID 36011051, 2022). "Thus, we did not detect an increased risk of the cancers which are associated to the BAP1 tumor predisposition syndrome." (PMID 35053448, 2022). "At present, we only know the BAP1 tumor predisposition syndrome, and this syndrome comprises only an insignificant fraction of the patients with accumulated cancers in our series, in accordance with a 3% occurrence of BAP1 variants in patients with posterior UM." (PMID 35053448, 2022). "This list includes 8 new additions to the existing group of syndromes from 2016, includingCarney complex, DICER1 syndrome, familial paraganglioma syndrome, melanoma-astrocytoma syndrome, familial retinoblastoma, BAP1 tumor predisposition syndrome, Fanconi anemia, and ELP1-medulloblastoma syndrome." (PMID 35969220, 2022). "Therefore, it is recommended that patients with germline BAP1 mutations and history of BAP1 tumor predisposition syndrome should obtain frequent surveillance images for meningioma." (PMID 34638590, 2021). "Additionally, germline BAP1 mutations are usually associated with aggressive rhabdoid meningioma and are also linked with BAP1 tumor predisposition syndrome." (PMID 34638590, 2021). "Breast cancer gene 1 (BRCA1)-Associated Protein Tumor Predisposition Syndrome (BAP1-TPDS) is a relatively newly discovered syndrome that may develop a variety of malignancies, including atypical melanoma resembling Spitz nevi." (PMID 34646590, 2021). "CM has also been described in a patient with the BAP1 tumor predisposition syndrome." (PMID 34071371, 2021). "Some groups recommend that, in patients who develop RCC at <46 years old, germline testing for BAP1 mutations may identify earlier BAP1-tumor predisposition syndrome patients and offer better surveillance." (PMID 32197306, 2020).
tumor predisposition syndrome (continued). "Data related to >180 families with germline BAP1 mutations have been collected in recent years, enabling identification of target organs, tumor types, and description of the BAP1 tumor predisposition syndrome (BAP1-TPDS, OMIM 614327) as a new hereditary cancer syndrome caused by BAP1 mutations." (PMID 32612654, 2020). "Also, a significant proportion of PeM patients might be affected by the so-called ‘BAP1 tumor predisposition syndrome’ (BAP1-TPDS), as they are carriers of a germline BAP1 mutation." (PMID 38642130, 2024). "The deubiquitinase BAP1 (BRCA1-associated protein 1) is associated with BAP1 tumor predisposition syndrome (TPDS)." (PMID 36980270, 2023). "Less common but significant high-risk genes include CDK4, a critical regulator of the cell cycle; BAP1 (BRCA1-associated protein 1), associated with BAP1 tumor predisposition syndrome; and telomere maintenance genes, such as TERT and POT1." (PMID 39941357, 2025). "BAP1 at 3p21.1 is involved in BRCA1-related tumor growth suppression, and germline mutations in patients with BAP1 tumor predisposition syndrome have been reported to be associated with familial RCC." (PMID 36011051, 2022). "Germline mutations in this gene are causative of the POT1 tumor-predisposition syndrome (POT1-TPD), which is characterized by a broad spectrum of malignancies, such as BAP1-TPDS." (PMID 34356093, 2021). "Germline mutations in BAP1 (BRCA1-Associated Protein 1) are associated with multiple types of hereditary cancers, which is now classified as BAP1-TPDS (BAP1 Tumor Predisposition Syndrome)." (PMID 32028647, 2020). "Squamous cell carcinoma is not a malignancy associated within the BAP1-tumor predisposition syndrome." (PMID 38090659, 2023). "While our patient did have a primary neuroendocrine tumor of the pancreas, this is not related to BAP1-tumor predisposition syndrome." (PMID 38090659, 2023). "While cutaneous melanoma is a part of the BAP1-tumor predisposition syndrome, this specific subtype has not been shown to have an association with BAP1 gene variations independent of the syndrome." (PMID 38090659, 2023). "Germline mutations in BAP1 are described in UM, but conjunctival melanoma is not part of the BAP1 tumor predisposition syndrome." (PMID 33396957, 2020). "Although the combination of MM and RCC is not characteristic of known tumor predisposition syndromes (e.g., von Hippel–Lindau, hereditary leiomyomatosis and RCC, Birt–Hogg–Dubé, BAP1 tumor predisposition), a germline mutation in a DNA-repair or tumor-suppressor gene cannot be excluded." (PMID 41562811, 2025).
renal cell carcinoma (103 papers, 2015 to 2026). "These cases underscore the clinical challenge posed by renal cell carcinoma with BAP1 loss at initial histological assessment." (PMID 41561288, 2025). "Within Group 2b cases, we confirmed the origin of two relevant TGVs: one germline ATM variant in a patient with papillary thyroid cancer and one somatic BAP1 variant in a patient with renal cell carcinoma." (PMID 39885482, 2025). "Germline BAP1 mutations have been found to be associated with both mesothelioma and renal cell carcinoma (RCC)." (PMID 41409117, 2025). "It is well known that a BAP1 germline variant predisposes patients to UM and other cancers, including cutaneous melanoma, malignant mesothelioma, meningioma, and renal cell carcinoma." (PMID 40283643, 2025). "NCT03786796) demonstrated that single-agent olaparib elicited responses in patients with renal cell carcinoma (RCC) harboring BAP1 or other DNA repair (DDR) gene mutations." (PMID 41440218, 2025). "In the context of renal cell carcinoma, BAP1 mutations correlate with cell proliferation, metastatic potential, high tumor grades, and unfavorable prognoses." (PMID 39457484, 2024). "Germline mutations in BAP1 were discovered in two families with a high incidence of mesothelioma and an elevated risk of malignancies, such as cutaneous melanoma, renal cell carcinoma, cholangiocarcinoma, and basal cell carcinoma." (PMID 37445575, 2023). "Other tumors associated with BAP1 germline mutations include renal cell carcinoma, lung carcinoma, meningioma, paraganglioma, cholangiocarcinoma, breast tumor, neuroendocrine carcinoma, gastric tumors, papillary adenoma and thyroid carcinomas, BCC and SCC." (PMID 34442055, 2021). "BAP1-deficient renal cell carcinoma cells were more sensitive to ionizing radiation than the BAP1 WT cells, although this difference was marginal." (PMID 30669483, 2019). "BAP1 mutations are associated with worse prognosis in uveal and cutaneous melanoma and renal cell carcinoma whereas they mark better outcomes for MMe patients." (PMID 30669483, 2019). "Between 2011 and 2013, germline BAP1 variants were also reported in association with cutaneous melanoma (CM), malignant mesothelioma (MMe), and renal cell carcinoma (RCC)." (PMID 31382694, 2019). "Our study indicate that common germline genetic variants of BAP1 play a role in mediating the risk of developing renal cell carcinoma and lung cancer." (PMID 29088836, 2017). "Overall, three BAP1 genetic variants were significant, two with the risk of renal cell carcinoma and one with the risk of lung cancer." (PMID 29088836, 2017). "BAP1 is also mutated in a fraction of uveal melanomas, renal cell carcinomas, and cholangiocarcinoma." (PMID 28756516, 2017). "Biallelic inactivation and mutations of BAP1 have been associated with a number of malignancies, including cutaneous melanocytic melanomas, mesothelioma and renal cell carcinomas." (PMID 26982343, 2016). "BAP1 has been identified as one of these predisposition genes, associated with a high susceptibility to various malignancies such as UM, malignant mesothelioma, cutaneous melanoma, renal cell carcinoma, meningioma, and other cancers." (PMID 40283643, 2025). "In the case of renal cell carcinoma, there is limited evidence suggesting that BAP1 mutations may be associated with improved progression-free survival when patients are treated with immunotherapy, as opposed to targeted therapies." (PMID 39939955, 2025). "However, multiple studies have shown that somatic loss of BAP1 in renal cell carcinoma is associated with a more aggressive clinical behaviour and worse prognosis." (PMID 37607989, 2023). "BAP1 (BRCA1-associated protein 1) with its gene product acting as a deubiquitinating enzyme, is a critical tumor suppressor gene that is mutated in various human cancers, including metastatic uveal melanoma, pleural mesothelioma, and renal cell carcinoma." (PMID 31635116, 2019).
renal cell carcinoma (continued). "Therefore, it is possible that rs11708581 and rs390802 affect the risk of developing renal cell carcinoma through BAP1." (PMID 29088836, 2017). "Expression quantitative trait loci analysis in renal cell carcinoma using publicly available data from TCGA showed that the proxy SNPs for rs11708581 and rs390802 were negatively associated with the expression level of BAP1." (PMID 29088836, 2017). "Screening renal ultrasound, MRI, or urinalysis for renal cell carcinoma could also be considered, as these patients are prone to renal cell carcinoma and BAP1 mutated renal tumors appear to grow at a faster rate than kidney cancers driven by other mutations such as in von Hippel-Lindau disease." (PMID 34504799, 2021). "New entities were described or better characterized, especially in kidney cancer such as hereditary leiomyomatosis renal cell carcinoma (HLRCC), succinate dehydrogenase kidney cancer (SDH-RCC), and more recently BAP1 germline mutation related RCC." (PMID 27819754, 2017). "Population studies of patients with cutaneous melanoma, ocular melanoma, malignant mesothelioma, and renal cell carcinoma identified BAP1 GPV in less than 1% of patients." (PMID 37607989, 2023). "BAP1-mutated CCRCC is a high-grade neoplasm with poor vascularization, including renal cell carcinoma with sarcomatoid and rhabdoid features." (PMID 37444462, 2023). "The BAP1-related cancer syndrome was discovered in individuals with germline altered BAP1 prone to additional cancer forms such renal cell carcinoma and squamous cell carcinoma." (PMID 38136277, 2023). "The probability of identifying a GPV in BAP1 is also low in most cases of renal cell carcinoma (RCC)." (PMID 37607989, 2023). "In renal cell carcinoma, knockout of BAP1 resulted in sensitization to apoptosis after γ-irradiation." (PMID 36420194, 2022). "Studying the effects of PARP1 inhibition in the other BAP1-mutant malignancies, such as renal cell carcinoma and cholangiocarcinoma, would be especially important, since cancers also have little beneficial therapy once initial resection has failed." (PMID 28756516, 2017). "BAP1-TPDS is associated with an increased risk for various malignant tumours, the core of which is uveal and cutaneous melanoma, malignant mesothelioma, and renal cell carcinoma." (PMID 41712014, 2026). "We searched novel genetic associations for predisposition to UM, additional to already studied BAP1 and MBD4, by using targeted amplicon sequencing of 19 genes associated with UM, BAP1, or renal cell carcinoma in 270 consecutively enrolled Finnish patients with UM." (PMID 39344744, 2025). "Similarly, peritoneal mesothelioma and renal cell carcinoma patients with BAP1 haploinsufficiency display an inflammatory microenvironment, characterized by increased immune cell tumor infiltration and enhanced PD-L1 expression." (PMID 37813891, 2023). "A meta-analysis of various cancer types with BAP1 mutations indicated that BAP1 mutations were also associated with worse outcomes in renal cell carcinoma but not in other cancers." (PMID 32028647, 2020). "From a therapeutic standpoint in renal cell carcinoma, inactivation of BAP1 sensitizes tumor cells to irradiation and PARP-inhibitors, which might be due to the impaired ability of double-stranded DNA breaks." (PMID 33585209, 2020). "In renal cell carcinoma, the amount of calcifications shows potential for predicting BAP1-status, which could be useful for assessing stage, grade and invasiveness." (PMID 29732009, 2018). "Renal cell carcinoma lacking BAP1 has also been found to be associated with a poor prognosis." (PMID 34616431, 2021). "Importantly, clarifying the biological mechanisms of resistance associated with absent BAP1 expression, an aberration increasingly linked to aggressive tumor behavior in renal cell carcinoma, may prove crucial in guiding future therapeutic approaches." (PMID 41561288, 2025).
renal cell carcinoma (continued). "Mechanistically, BAP1 has been found to deubiquitylate both gamma‐tubulin in breast cancer and the centrosome protein MCRS1 in renal cell carcinoma, affecting the mitotic spindle and centrosome formation." (PMID 35474453, 2022). "(B) The BAP1-wild-type breast cancer line MDAMB-231 and the renal cell carcinoma (RCC) lines Caki-1 and BB65 were transduced with BAP1 (shBAP1) or empty vector (EV) shRNA." (PMID 29345617, 2018). "Poly(ADP-ribose) polymerase (PARP) inhibition in renal cell carcinoma (RCC) is biologically plausible via synthetic lethality in tumors with impaired DNA-damage repair (DDR), notably BAP1 and other DDR lesions, yet clinical translation in metastatic RCC (mRCC) remains preliminary." (PMID 41440218, 2025). "The cited authors report that VHL, BAP1, FH, and MET are specific genes that increase the risk of developing renal cell cancer, whereas CHEK2, MUTYH, APC, and STK1 are not typically associated with the development of renal tumours." (PMID 39336594, 2024).
cutaneous melanoma (102 papers, 2012 to 2026). A primary melanoma arising from atypical melanocytes in the skin. "The BAP1 gene (MIM# 606661) is implicated in approximately 1% of cutaneous melanomas and 4% of uveal melanomas." (PMID 40558591, 2025). "Low BAP1 mRNA expression levels were reported to be associated with worse survival in some cutaneous melanoma patient cohorts, while in others, low BAP1 mRNA expression was associated with better overall survival." (PMID 38903495, 2024). "BAP1 tumor predisposition syndrome (BAP1) is a newly recognized cancer syndrome that predisposes to uveal and cutaneous melanoma (36% and 12–45%, respectively)." (PMID 37239385, 2023). "Whilst BAP1 loss is uncommon in skin melanoma, it is associated with a subset of cutaneous non‐melanoma tumours called BAP1‐inactivated melanocytic tumours (BIMTs)." (PMID 35474453, 2022). "Germline mutations in CDKN2A as well as BAP1 carry not only an increased risk for the development of MPM, but also for uveal or cutaneous melanoma and, in the case of BAP1, a wide range of other tumors." (PMID 35205798, 2022). "Other tumors such as BAP-oma, cutaneous melanoma, mesothelioma, and/or renal cell carcinoma have also been related to this alteration and constitute the BAP1 related tumor predisposition syndrome." (PMID 34771510, 2021). "Germline pathogenic variants and somatic mutations in the BAP1 gene have been described in ocular and cutaneous melanoma and paralleled with a highly aggressive ocular melanoma phenotype but also detected in several other cancer subtypes." (PMID 33578810, 2021). "Individuals who carry the mutated BAP1 gene develop melanocytic lesions later in life, and some of those benign lesions can transform into cutaneous melanomas." (PMID 33800394, 2021). "In familial UM as well as families in which UM is present and family members known with malignant mesothelioma, cutaneous melanoma, clear cell renal cell carcinoma and basal cell carcinoma, an underlying germline mutation in BAP1, can be present." (PMID 33396957, 2020). "Germline BAP1 mutations define the recently identified BAP1 cancer syndrome with affected patients developing different tumor entities, such as uveal and cutaneous melanoma, malignant mesothelioma, atypical Spitz tumors and others." (PMID 31635116, 2019). "Germline mutations in the BAP1 are associated with increased risks of malignant mesothelioma as well as uveal and cutaneous melanoma, whereas somatic mutations in this gene have been detected in various types of tumors including PGLs." (PMID 29504908, 2018). "Carriers of germline BAP1 mutations have a very high incidence of cancer, most commonly uveal melanoma, malignant mesothelioma, cutaneous melanoma and clear cell renal cell carcinoma." (PMID 30001711, 2018). "Germline BAP1 alleles defined as loss-of-function or predicted to be deleterious/damaging are rare in cutaneous melanoma." (PMID 28062663, 2017). "BAP1 (BRCA1-associated protein-1/ubiquitin carboxy-terminal hydrolase) is involved in metastatic progression of ocular and cutaneous melanoma." (PMID 24743024, 2014). "Subsequently, five families with deleterious germline BAP1 mutations were also described including several kindreds with both ocular and cutaneous melanoma (CM)." (PMID 22545102, 2012). "The role of BAP1 in cutaneous melanoma is still being studied, and the implications of mutations in this gene on tumor response to targeted cancer therapies remain unclear." (PMID 40842586, 2025). "Also, the cutaneous melanomas showed functional inactivation (by mutation or epigenetic mechanisms) of BAP1." (PMID 28404968, 2017). "However, patients carrying germline BAP1 mutations in PMe and cutaneous melanoma show an improved survival and a better prognosis, suggesting that the presence of a mutated BAP1 might mitigate tumour aggressiveness (a “friendly” aspect)." (PMID 38459714, 2024).